PLS3 (plastin 3)
Diseases named in the same sentence as PLS3 in open-access papers (continued):
Sharing a sentence is not in itself a finding about the gene and the disease.
gastric cancer (9 papers, 2016 to 2025). A primary or metastatic malignant neoplasm involving the stomach. "In gastric cancer, increased expression of PLS3 indicates a poor prognosis and is associated with cancer differentiation, the depth of tumor invasion and EMT." (PMID 34023917, 2021). "ZNF471 suppresses gastric cancer by transcriptionally repressing the PLS3 and TFAP2A downstream oncogenes." (PMID 39695171, 2024). "In vitro, gastric cancer cell lines transduced with PLS3 siRNA exhibited reduced migration and invasiveness." (PMID 31717802, 2019). "We demonstrated the oncogenic properties of TFAP2A in promoting cell proliferation, migration and invasion and PLS3 in inducing cell migration and invasion in gastric cancer cell lines." (PMID 29610526, 2018). "Taken the EMSA and GSEA results together, we therefore focused on the functional role of TFAP2A and PLS3 in gastric cancer." (PMID 29610526, 2018). "TFAP2A and PLS3 showed oncogenic functions in gastric cancer cell lines." (PMID 29610526, 2018). "Similarly, knocking down PLS3 in gastric cancer cells, significantly attenuated cell migration and invasion ability of BGC823 and MKN74 cells." (PMID 29610526, 2018). "The zinc-finger protein 471 was shown to inhibit gastric cancer progression through transcriptionally repressing downstream PLS3 and TFAP2A, suggesting that TFAP2A and PLS3 act as oncogenic factors in gastric cancer cell development." (PMID 36707053, 2023). "ZNF471 acts as a tumor suppressor in gastric cancer by transcriptionally inhibiting downstream targets TFAP2A and PLS3." (PMID 33133131, 2020). "Combining the EMSA result and GSEA with TCGA Stomach Cancer gene expression RNAseq data, we identified TFAP2A and PLS3, as the critical targets of ZNF471." (PMID 29610526, 2018). "In conclusion, ZNF471 acts as a tumor suppressor in gastric cancer by transcriptionally inhibiting downstream targets TFAP2A and PLS3." (PMID 29610526, 2018). "Taken together, KAP1 serves as a co-repressor for ZNF471 in gastric cancer, inducing elevated H3K9me3 in the promoter of TFAP2A and PLS3." (PMID 29610526, 2018). "Interestingly, LOXL1 downregulates CDH1 and upregulates VIM, CDH2, PLS3, and SNAI2 in gastric cancer cells, where expression of LOXL1 correlates with EMT." (PMID 34023917, 2021). "Hence, ZNF471 suppressed gastric cancer progression by transcriptionally repressing its downstream targets TFAP2A and PLS3 in co-operating with KAP1." (PMID 29610526, 2018).
acute myeloid leukemia (4 papers, 2019 to 2021). Acute myeloid leukemia (AML) is a group of neoplasms arising from precursor cells committed to the myeloid cell-line differentiation. "We have identified the actin-binding protein Plastin-3 (PLS3) as potential player within the leukemic bone marrow niche and investigated its functional role in acute myeloid leukemia." (PMID 31717802, 2019). "In the current study, the actin binding protein PLS3 was identified as potential player in acute myeloid leukemia." (PMID 31717802, 2019). "Taken together, we could identify the actin binding protein PLS3 as potential player for the establishment and maintenance of acute myeloid leukemia." (PMID 31717802, 2019). "We could identify the actin binding protein PLS3 as potential player for the establishment and maintenance of acute myeloid leukemia." (PMID 31717802, 2019). "In the current study, we investigated the impact of Plastin-3 (PLS3) in acute myeloid leukemia as we had identified PLS3 as potential player within the leukemic bone marrow niche through gene expression analysis of AML and endothelial cell co-cultures." (PMID 31717802, 2019). "Elevated PLS3 expression is a negative prognostic marker for acute myeloid leukemia (AML), the most common acute leukemia in adults, while knockdown of PLS3 increases survival in vivo." (PMID 34023917, 2021).
colon carcinoma (4 papers, 2008 to 2021). "Interestingly, the polymorphism SNP PLS3 rs871773 T allele is associated with a higher protein expression of the PLS3 gene in colon cancer and an increased risk of recurrence of colon cancer." (PMID 26134627, 2015). "Additionally, the PLS3 mutation, rs871773, that increases PLS3 expression in colon cancer does not associate with mild SMA exception cases." (PMID 34445199, 2021).
osteoarthritis (4 papers, 2020 to 2023). A noninflammatory degenerative joint disease occurring chiefly in older persons, characterized by degeneration of the articular cartilage, hypertrophy of bone at the margins and changes in the synovial membrane. "An interference of the mechanotransduction process is a crucial factor associated with the pathogenesis of osteoarthritis, where also the impact of PLS3 on the actin cytoskeleton is suggested to play an essential role." (PMID 34023917, 2021). "However, in wild-type condition, overexpression of PLS3 is detrimental and causes osteoarthritis or facilitates cancer." (PMID 34023917, 2021). "In contrast, an upregulation of PLS3 on wild-type level might cause osteoarthritis." (PMID 34023917, 2021). "In 2015, increased PLS3 levels have been reported in chondrocytes from patients with osteoarthritis compared to healthy individuals." (PMID 34023917, 2021). "Furthermore, the RANKL–RANK pathway plays a crucial role not only in osteoarthritis in general, but seems to be stressed in osteoarthritis patients showing increased PLS3 levels." (PMID 34023917, 2021).
Ataxia (3 papers, 2019 to 2021). Ataxia refers to impaired coordination of voluntary muscle movement. "In conclusion, this study reveals that PLS3 OE is a disease modifier for ataxia caused by Chp1-depletion." (PMID 31607845, 2019). "Thus, PLS3 overexpression has a moderate protective effect on ataxia caused by Chp1 depletion and demonstrates its potential as a cross-disease modifier." (PMID 34023917, 2021). "Indeed, recently we reported that PLS3 overexpression is beneficial in CHP1-related ataxia in mice that carry biallelic Chp1 mutation." (PMID 32938453, 2020). "In this study, we aimed to determine whether PLS3 is a cross-disease modifier for ataxia caused by Chp1 mutation in mice." (PMID 31607845, 2019). "Since, it has been shown that PLS3 directly interacts with CHP1, and CHP1 depletion causes ataxia in the vacillator mouse model, we hypothesized that PLS3 OE may improve the ataxic phenotype in vivo." (PMID 31607845, 2019). "PLS3 overexpression increases membrane targeting of NHE1, an important binding partner of CHP1 that is also associated with ataxia when mutated, at an early disease stage." (PMID 34023917, 2021). "Nevertheless, this study highlights the involvement of PLS3 OE as a cross-disease modifier for neurodegenerative diseases, including SMA and CHP1-associated ataxia." (PMID 31607845, 2019). "Among them, PLS3 directly interacts with calcineurin like EF-hand protein 1 (CHP1), whose loss-of-function results in ataxia." (PMID 31607845, 2019). "Since PLS3 has been shown to directly interact with CHP1, in this study we investigated whether PLS3 is a cross-disease modifier for ataxia caused by Chp1 mutation in mice." (PMID 31607845, 2019). "Mechanistically, we found that PLS3 OE in the cerebellum shows a trend of increased membrane targeting and/or expression of Na+/H+ exchanger (NHE1), an important CHP1 binding partner and a causative gene for ataxia, when mutated in humans and mice." (PMID 31607845, 2019). "It remains hitherto unknown, how exactly PLS3 OE delays the ataxia progression at an early stage." (PMID 31607845, 2019). "PLS3 is an important interaction partner of several proteins or protein complexes involved in neurodegeneration disorders such as SMA, ataxia, amyotrophic lateral sclerosis (ALS), and Charcot–Marie–Tooth (CMT)." (PMID 34023917, 2021). "Furthermore, understanding the interaction between PLS3 and SMN could provide insight into other neurodegenerative diseases including ataxia and amyotrophic lateral sclerosis (ALS)." (PMID 32938453, 2020).
cutaneous T cell lymphomas (3 papers, 2019 to 2024). "For example, in patients with Sezary syndrome, a leukemic and erythrodermic variant of cutaneous T cell lymphomas, upregulation of PLS3 has been observed which is in part due to the hypomethylation of the PLS3 promoter." (PMID 31717802, 2019). "Notably, PLS3 is ectopically expressed in Sézary syndrome tumor cells, a leukemic variant of cutaneous T-cell lymphomas, but remains uninvestigated in other T-cell lymphomas." (PMID 38012392, 2024).
idiopathic osteoporosis (3 papers, 2018 to 2023). "Interestingly, a pathogenic variant of PLS3 has recently also been described in a patient with idiopathic osteoporosis and ASD53." (PMID 34031387, 2021).
lung carcinoma (3 papers, 2020 to 2025). "Some of these genes were previously shown to be prognostic biomarkers in different tumors, for example, high CANT1 expression was related to a poor prognosis in prostate and lung carcinomas, and PLS3 may be useful as a biomarker for identifying recurrences or a poor prognosis in some cancers." (PMID 34076352, 2021).
Sezary syndrome (3 papers, 2015 to 2022). Sezary syndrome (SS) is an aggressive form of cutaneous T-cell lymphoma characterized by a triad of erythroderma, lymphadenopathy and circulating atypical lymphocytes (Sezary cells). "High PLS3 levels have also been found in Sezary Syndrome patients and this was associated with loss of CD26." (PMID 26134627, 2015).
autism (2 papers, 2018 to 2025). Persistent deficits in social interaction and communication and interaction as well as a markedly restricted repertoire of activity and interest as well as repetitive patterns of behavior. "NBAS is known to cause SOPH syndrome and PLS3 are known to be associated with heritable bone fragility but autism is not a known association with these genes." (PMID 29955634, 2018). "Both epilepsy and autism have been reported before in three studies of patients with OI and PLS3 genetic variants, suggesting but not proving that neurological abnormalities may be linked to genetic causes of bone fragility." (PMID 40353206, 2025).
metastatic colorectal cancer (2 papers, 2019 to 2022). "A previous study showed that the expression of PLS3 by circulating tumor cells was a marker in metastatic colorectal cancer." (PMID 35409173, 2022). "PLS3 expression on circulating tumor cells was described in metastatic colorectal cancer patients." (PMID 31717802, 2019).
non-small cell lung carcinoma (2 papers, 2021). A group of at least three distinct histological types of lung cancer, including non-small cell squamous cell carcinoma, adenocarcinoma, and large cell carcinoma. "Besides, PLS3 has been proven to be a prognostic and/or diagnostic tumor marker also in other tumor entities, e.g., non-small-cell lung cancer (NSCLC) or pancreatic ductal adenocarcinoma (PDAC)." (PMID 35008210, 2021). "In non-small-cell lung cancer (NSCLC), increased PLS3 plasma levels are a predictor of poor survival." (PMID 34023917, 2021).
pancreatic cancer (2 papers, 2020 to 2025). "Prior research has suggested in thyroid cancer, PLS3 triggers the Notch signaling pathway to promote malignant progression; in pancreatic cancer, it enhances cancer cell proliferation through PI3K/AKT signaling." (PMID 41375083, 2025). "Within pancreatic cancer, PLS3 facilitates tumor cell proliferation through activating the PI3K/AKT pathway." (PMID 41375083, 2025). "One gene, SLC2A1, is present in five tumor entities (renal, urothelial, lung, liver and pancreatic cancer) and PLS3, SLC16a1, and SLC16A3 are present in four tumor entities." (PMID 32599841, 2020).
triple-negative breast carcinoma (2 papers, 2019 to 2021). An invasive breast carcinoma which is negative for expression of estrogen receptor (ER), progesterone receptor (PR), and human epidermal growth factor receptor 2 (HER2). "Silencing of PLS3 in MDA-MB-231 triple-negative breast cancer cells increases the sensitivity towards the anti-cancer agent paclitaxel." (PMID 34023917, 2021). "PLS3 overexpression is found in two-third of CTCs from breast cancer patients in different stages of EMT and is associated with poor overall survival, especially in patients with luminal type A or triple-negative breast cancer." (PMID 34023917, 2021). "For example, Ma and colleagues could show that PLS3 silencing in triple-negative breast cancer cells increased the sensitivity to paclitaxel via the p38 MAPK signaling cascade." (PMID 31717802, 2019).
bladder cancer (1 paper, 2019). "Furthermore, the reduction of PLS3 expression using antisense RNA in a bladder cancer cell line was associated with increased sensitivity to cisplatin." (PMID 31717802, 2019).
Camurati-Engelmann disease (1 paper, 2021). Camurati-Englemann disease (CED) is a rare, clinically variable bone dysplasia syndrome characterized by hyperostosis of the long bones, skull, spine and pelvis, associated with severe pain in the extremities, a wide-based waddling gait, joint contractures, muscle weakness and easy fatigability. "A total of 7/47 probands suspected with OI carried variants in 6 disease-causing genes, namely, 1 IFITM5, 1 CRTAP, 2 BMP1, 1 PLS3, and 1 COL1A2 (c.432 + 4_432 + 7delAGTA was ignored previously), and 1 case of Camurati-Engelmann disease with pathogenic variants in TGFβ-1, which was misdiagnosed." (PMID 34557487, 2021).
endometriosis (1 paper, 2025). The growth of functional endometrial tissue in anatomic sites outside the uterine body. "Notably, PLS3 expression is elevated in the endometrium during the secretory phase in women with minimal or mild endometriosis compared to disease-free controls." (PMID 40072086, 2025).
gastric tumor (1 paper, 2018). "Collectively, these findings suggested that ZNF471 is a novel gastric tumor suppressor which functions by transcriptional inhibition of its oncogenic targets, TFAP2A and PLS3." (PMID 29610526, 2018).
glioblastoma (1 paper, 2012). The most malignant astrocytic tumor (WHO grade IV). "At the level of individual GNS signature genes, five were significantly associated with survival (P < 0.05) in both of the two largest glioblastoma data sets we investigated (TCGA and Gravendeel): HOXD10, PDE1C, PLS3, PTEN and TUSC3." (PMID 23046790, 2012). "Specifically, DDIT3, HOXD10, PDE1C and PLS3 were upregulated in GNS cells and expressed at higher levels in glioblastomas with poor prognosis, while PTEN and TUSC3 were downregulated in GNS cells and expressed at lower levels in gliomas with poor prognosis." (PMID 23046790, 2012).
leukemia (1 paper, 2019). A malignant (clonal) hematologic disorder, involving hematopoietic stem cells and characterized by the presence of primitive or atypical myeloid or lymphoid cells in the bone marrow and the blood. "Further studies should focus on the underlying leukemia-promoting mechanisms and investigate PLS3 as therapeutic target." (PMID 31717802, 2019). "Further studies should focus on the underlying leukemia-promoting molecular mechanisms and PLS3 should be investigated as therapeutic target." (PMID 31717802, 2019). "PLS3 might mediate its leukemia-promoting effects in our study at least partly through activation of cMYC." (PMID 31717802, 2019). "In order to get more insight into the signaling cascades PLS3 might be involved in leukemia, we performed RNA sequencing of Kasumi-1 PLS3-sh1 and PLS3-sh2 knockdown vs. control cells." (PMID 31717802, 2019). "More importantly, three animals of the knockdown group did never develop a leukemia confirming our hypothesis that PLS3 is important for the leukemic engraftment." (PMID 31717802, 2019).
motor neuron diseases (1 paper, 2020). "The identification and functional interaction identified between SMN, PLS3, and hnRNP F/H provide insight into the mechanisms that lead to perturbations in motor neuron disease." (PMID 32938453, 2020). "In addition, the suppression of ALS behavioral defects in a C. elegans model by increasing PLS3 or decreasing SYM-2 expression shows that conserved pathways are affected across motor neuron diseases." (PMID 32938453, 2020). "Taken together, these results indicate that PLS3 overexpression is not generically beneficial and ameliorating endocytic pathways may improve function in C. elegans models of motor neuron disease." (PMID 32938453, 2020).
osteosarcoma (1 paper, 2023). A usually aggressive malignant bone-forming mesenchymal neoplasm, predominantly affecting adolescents and young adults. "However, this experiment was done in U2OS osteosarcoma cells that were plated on glass and that were expressing endogenous levels of PLS3, raising the question how these mutants would behave in the absence of WT PLS3 and in cells plated on substrates with different stiffnesses." (PMID 38089885, 2023).
pancreatic ductal adenocarcinoma (1 paper, 2021). An infiltrating adenocarcinoma that arises from the epithelial cells of the pancreas. "Altered Plastin-3 (PLS3; an actin-binding protein) expression was associated with human carcinogenesis, including pancreatic ductal adenocarcinoma (PDA)." (PMID 34348730, 2021).
pancreatic lymphoma (1 paper, 2021). "Moreover, low levels of PLS3 expression may prevent accurate PPL diagnosis because of the inability to rule out the possibility of secondary pancreatic lymphoma." (PMID 34348730, 2021).
Patent ductus arteriosus (1 paper, 2023). In utero, the ductus arteriosus (DA) serves to divert ventricular output away from the lungs and toward the placenta by connecting the main pulmonary artery to the descending aorta. "Besides, PLS3 mutations were reported to have patent ductus arteriosus." (PMID 37083757, 2023).
prostate carcinoma (1 paper, 2021). A carcinoma that arises from epithelial cells of the prostate gland. "For prostate cancer, a gene panel with 14 genes has been developed including PLS3, VIM, and CDH2, and in 9.5% of patients an increased expression of PLS3 has been found." (PMID 34023917, 2021).
scoliosis (1 paper, 2022). A congenital or acquired spinal deformity characterized by lateral curvature of the spine. "In the present study, we identified a novel PLS3 splicing mutation in a patient with early-onset osteoporotic fracture and scoliosis." (PMID 35752817, 2022). "Scoliosis represents a potential new phenotype in the patients harboring PLS3 mutations, which may be corrected by brace treatment." (PMID 35752817, 2022).